ABHD16A (abhydrolase domain containing 16A, phospholipase)
Description:
Phosphatidylserine (PS) lipase that mediates the hydrolysis of phosphatidylserine to generate lysophosphatidylserine (LPS) (By similarity). LPS constitutes a class of signaling lipids that regulates immunological and neurological processes (By similarity). Has no activity towards diacylglycerol, triacylglycerol or lysophosphatidylserine lipase. Also has monoacylglycerol lipase activity, with preference for 1-(9Z,12Z-octadecadienoyl)-glycerol (1-LG) and 2-glyceryl-15-deoxy-Delta(12,14)- prostaglandin J2 (15d-PGJ(2)-G).
Synonyms: hBAT5; BAT5; NG26; PP199; D6S82E; SPG86
Tractability: Small molecule: a high-quality ligand is known; it belongs to a druggable protein family. Antibody: UniProt predicts a signal peptide or a membrane-spanning region. PROTAC: ubiquitination databases record sites on it; its protein half-life has been measured; a small molecule that binds it is known.
Target class: Enzyme; Hydrolase
Gene: Protein-coding gene on chromosome 6 (31,686,954 to 31,703,356, reverse strand). Ensembl gene ENSG00000204427.
Subcellular location: Membrane
Gene Ontology:
Molecular function: monoacylglycerol lipase activity; phosphatidylcholine lysophospholipase activity; protein binding; phospholipase activity
Biological process: monoacylglycerol catabolic process; prostaglandin catabolic process; phosphatidylserine catabolic process
Cellular component: membrane
Genetic constraint (gnomAD): Loss-of-function variants: 47 observed, 87.43 expected, observed/expected ratio (o/e) 0.54, 90% interval 0.43 to 0.69. The upper end of that interval is the gene's LOEUF score, 0.69, which puts it in group 2 of 6, group 1 being the genes least tolerant of losing a copy. Missense variants: 580 observed, 725.86 expected, observed/expected ratio (o/e) 0.8, 90% interval 0.75 to 0.86. Synonymous variants: 251 observed, 273.72 expected, observed/expected ratio (o/e) 0.92, 90% interval 0.83 to 1.02.
Homologues: Orthologues: chimpanzee ABHD16A (97% identical), pig ABHD16A (97% identical), mouse Abhd16a (96% identical), guinea pig ABHD16A (96% identical), macaque ABHD16A (95% identical), rabbit ABHD16A (94% identical), rat Abhd16a (92% identical), dog ABHD16A (87% identical), tropical clawed frog abhd16a (72% identical), zebrafish abhd16a (66% identical), Drosophila melanogaster CG1309 (40% identical), Caenorhabditis elegans F37A4.1 (31% identical), and 2 more. Paralogues in human: ABHD16B (46% identical), ABHD12B (13% identical), ABHD12 (12% identical), ABHD17A (9% identical), ABHD13 (9% identical), ABHD17C (9% identical), ABHD17B (9% identical).
Diseases named in the same sentence as ABHD16A in open-access papers:
ABHD16A is named in the same sentence as 12 diseases in open-access papers, as found by Europe PMC text mining. Sharing a sentence is not in itself a finding about the gene and the disease. The quoted sentences say what the papers report.
virus infection (3 papers, 2022 to 2025). "Nevertheless, the molecular mechanism underlying the regulation of ABHD16A during virus infection remains to be elucidated." (PMID 39601593, 2025). "Combined with the dynamic palmitoylation/depalmitoylation modification playing key roles in host-virus interaction, we decided to verify whether and how ABHD16A regulates virus infection." (PMID 40434075, 2025). "Our study reveals a novel mechanism of IFITM against virus invasion and suggests RNF5 as well as ABHD16A may act as promising therapeutic targets for the intervention of virus infection." (PMID 39601593, 2025). "Collectively, these data revealed depletion of ABHD16A reduce virus infection." (PMID 36314839, 2022). "Moreover, we adopted another two RNA viruses to reveal the role of ABHD16A in regulating virus infection." (PMID 36314839, 2022). "Our findings provide new insights into the mechanisms of IFITMs fighting against virus; demonstrate the importance of RNF5, ABHD16A, and IFITM interplay in balancing antiviral immune responses; and provide broad-spectrum therapeutic strategies for animal viral diseases." (PMID 39601593, 2025). "Although ABHD16A has been reported to play roles in the immune regulation for decades, whether ABHD16A mediates viral infection has not yet been answered for a long time." (PMID 39601593, 2025).
complex hereditary spastic paraplegia (1 paper, 2023). A hereditary spastic paraplegia that is part of a larger syndrome. "ABHD16A, also known as Human Lymphocyte Antigen B-associated transcript 5 (BAT5), is a phosphatidylserine lipase recently identified as a novel protein depalmitoylating enzyme that has been linked to complex hereditary spastic paraplegia (HSP)." (PMID 37324388, 2023).
gastric cancer (1 paper, 2021). A primary or metastatic malignant neoplasm involving the stomach. "Intriguingly, in gastric cancer, we confirmed that ABHD16A involves in tumor lipid metabolism, which causes metabolite lyso-PS accumulation to promote cancer metastasis." (PMID 33875796, 2021). "As ABHD16A is a novel phosphatidylserine-specific lipase which involves in lipid metabolism, we asked whether the effect of ABHD16A on gastric cancer metastasis was caused by altered lipid metabolites." (PMID 33875796, 2021). "The purpose of our study was to explore the effect of mirtronic miR-4646-5p and its host gene Abhd16a on lipid metabolism and gastric cancer metastasis." (PMID 33875796, 2021). "Taken together, these data demonstrate that ABHD16A, as a novel phosphatidylserine-specific lipase, plays an essential role to fuel gastric cancer metastasis via regulating lyso-PS accumulation in lipid metabolism." (PMID 33875796, 2021). "In general, our research highlights the feedback regulation between mirtronic miR-4646-5p and its host gene Abhd16a, and their function in lipid metabolism and metastasis of gastric cancer." (PMID 33875796, 2021). "Taken together, miR-4646-5p/PHD3/HIF1A axis upregulates RhoA transcription and the RhoA activation can be triggered by miR-4646-5p/ABHD16A-mediated lipid metabolite lyso-PS accumulation in gastric cancer cells." (PMID 33875796, 2021). "MiR-4646-5p and its host gene Abhd16a mediated abnormal lipid metabolism may be a new target for clinical treatment of gastric cancer." (PMID 33875796, 2021). "Here, we unveiled the functions of another aberrant mirtronic miR-4646-5p and its host gene Abhydrolase domain containing 16A (Abhd16a) in GC, which may shed light on gastric cancer malignancy and metastasis." (PMID 33875796, 2021). "ABHD16A, as an emerging phosphatidylserine-specific lipase, involves in lipid metabolism leading to lysophosphatidylserines (lyso-PSs) accumulation, which stimulates RhoA and downstream LIMK/cofilin cascade activity through GPR34/Gi subunit, thus causes metastasis of gastric cancer." (PMID 33875796, 2021). "Namely, miR-4646-5p feedback promotes Abhd16a mRNA transcription and expression of ABHD16A protein, involving in lipid metabolism to cause lyso-PS accumulation, thus stimulates activation of GPR34 receptor to trigger RhoA/LIMK/cofilin signaling in fueling gastric cancer metastasis." (PMID 33875796, 2021). "To further validate the role of ABHD16A in promoting gastric cancer metastasis, we generated the engineered gastric cells including GC cells with ectopic Abhd16a (Drosha WT/ABHD16A), and Abhd16a and Drosha doubly knocked down cells (Drosha KD/ABHD16A KD)." (PMID 33875796, 2021).
Kawasaki disease (1 paper, 2023). A rare inflammatory disease characterized by an acute febrile, systemic, self-limiting, medium-vessel vasculitis primarily affecting children. "ABHD16A is a member of the alpha/beta hydrolase domain-containing protein family that is involved in Kawasaki disease." (PMID 37245199, 2023).
cancer (2 papers, 2021 to 2023). A tumor composed of atypical neoplastic, often pleomorphic cells that invade other tissues. "ABHD16A is an emerging enzyme, mainly involved in lipid metabolism and intracellular signaling, leading to the metastasis of cancer." (PMID 36819030, 2023).
liver (1 paper, 2021). "Conversely, knockdown of miR-4646-5p or Abhd16a in Drosha silenced GC cells notably attenuated the lyso-PS concentration in lung and liver metastases, while this reduction could be rescued by exogenous supplementation of lyso-PS." (PMID 33875796, 2021).
tumor (1 paper, 2021). "Additionally, ABHD16A levels were higher in tumor with distant metastasis (M1) than tumor in site (M0) by analysis of STAD data from UCSC Xena." (PMID 33875796, 2021). "However, whether ABHD16A has a function in tumors, especially, ABHD16A-mediated lipid metabolism contributing to tumor development and metastasis remains largely unknown." (PMID 33875796, 2021).
ABHD16A also shares sentences with these, for which no sentence is quoted: cardiovascular disorder (1 paper); gastric tumor (1); hereditary spastic paraplegia (1); Hypertension (1); viral diseases (1).